IL5 (interleukin 5)
Diseases named in the same sentence as IL5 in open-access papers (continued):
Sharing a sentence is not in itself a finding about the gene and the disease.
polyp (24 papers, 2009 to 2025). A usually exophytic mass attached to the underlying tissue by a broad base or a thin stalk. "Both IL-5 and IL-13 are elevated in polyp sinonasal tissue extracts compared with controls, and IL-5 immunoreactivity was previously found to be restricted to MCTs in asthmatic bronchial mucosal biopsies." (PMID 39744949, 2025). "Persistent elevation of IL-5, IL-13, and other pro-inflammatory cytokines correlates with increased polyp size, greater symptom burden, and reduced treatment responsiveness." (PMID 39328679, 2024). "Nasal polyp size was reduced after using reslizumab, especially in patients with raised intranasal interleukin-5 (IL-5) levels." (PMID 39687236, 2024). "For instance, IL-5 is a potent stimulator of eosinophilic growth as well as proliferation, and the concentration of IL-5 is significantly higher in polyp tissues." (PMID 37138733, 2023). "T helper type 2 releasing cytokines, interleukins (IL-5 and IL-13), as well as histamine, are frequently found in high concentrations in polyp tissue." (PMID 37605661, 2023). "Several authors have demonstrated that high eosinophilic infiltration and high IL-5 expression in CRSwNP correlates with a higher rate of polyp recurrence." (PMID 36013200, 2022). "Signature Th1 (IFN-γ), Th2 (IL-5 and IL-13), and Th17 (IL-17A) cytokines were measured in iNKT cells from four inflammatory subtypes of polyp tissues." (PMID 35720287, 2022). "The anti-IL-5 mAb, reslizumab reduced the polyp size, blood eosinophilic counts, and ECP concentration in nasal secretions." (PMID 30778348, 2019). "The results showed that the levels of Th2 cytokine, including IL-4, IL-5 and IL-4, were significantly higher in polyp group than in the healthy group, while the levels of IFN-γ we're not different from each other." (PMID 28388587, 2017). "IL-5 is a potent activator of eosinophils, the dominant immune cell type in polyp tissue in Western populations of CRS patients." (PMID 28494786, 2017). "Expressions of IFN-γ, IL-5, IL-17A, IL-25 and IL-10 were significantly higher in the 3 months and 6 months murine polyp model than in the control mice." (PMID 27584662, 2016). "The release of IL-5 in polyp tissue from patients with CRSwNP (6.9±1.2 pg/ml) were significantly higher compared to the release in turbinate tissue from both healthy controls (0.6±0.0 pg/ml, P<0.001) and patients with CRSwNP (0.7±0.1 pg/ml, P<0.001)." (PMID 25133733, 2014). "Other groups have demonstrated a higher release of IL-5 and IL-10 in polyp tissue than in turbinate tissue from healthy controls." (PMID 25133733, 2014). "A recent study composed a combined model and predicted polyp recurrence after standard endoscopic sinus surgery, quantifying the prognostic value of eosinophil cationic protein, IL-5, pre-endoscopic sinus surgery-modified Lund–MacKay score, asthma, and anti-dsDNA IgG." (PMID 37569753, 2023). "In addition, the number of Tregs in PBMCs is negatively correlated with Th1- and Th2-related cytokines (such as INF-γ, IL-4, and IL-5) in polyp tissues." (PMID 35378904, 2022). "Improvements were seen in rhinosinusitis outcome measure scores, extent of the disease on magnetic resonance imaging scanning, reduction in polyp size, and levels of eosinophil cationic protein (ECP), interleukin 5 and IgE in nasal secretions." (PMID 25379119, 2014). "The number of Tregs is negatively associated with Th1- and Th2-related cytokines (such as INF-γ, IL-4, and IL-5) in polyp tissues in both atopic and nonatopic patients." (PMID 35378904, 2022).
autoimmune disease (23 papers, 2006 to 2025). A disorder resulting from loss of function or tissue destruction of an organ or multiple organs, arising from humoral or cellular immune responses of the individual to their own tissue constituents. "The IL5 rs2069812 polymorphism has also been studied in other autoimmune diseases." (PMID 36361964, 2022). "Although IL-17E is known to induce a Th2-mediated allergic response by stimulating IL-4, IL-5 and IL-13 production, several studies highlight its proinflammatory role in skin and autoimmune diseases." (PMID 38799435, 2024). "In the event of infection with helminth parasites, IL-5 leads to a lesser risk of autoimmune disorders, which is indirectly accredited to some therapeutic characteristics of IL-5 in autoimmune disorders." (PMID 32102262, 2020). "Over the past decade, the concept of targeting cytokines to treat autoimmune diseases has evolved at a rapid pace, such as some medicines approved by the drug administration to target IL-1β, IL-5, IL-6, IL-2, TNF-α, and IFN-γ." (PMID 29250557, 2017). "The interleukin-5 (IL-5) rs2069812 single-nucleotide polymorphism (SNP) seems to define the clinical course of Th2 autoimmune diseases, while its role in MS has never been investigated." (PMID 39201794, 2024). "Patients with lupus nephritis, an organ-specific autoimmune disease, have increased levels of IL-5 in their urine, suggesting that IL-5 may be involved in eosinophil recruitment in these patients." (PMID 39337564, 2024). "The evaluated cytokines can be classified into three broad groups: the proinflammatory Th-1 cytokines: IL-2, IFN-γ, and TNF-α; the counterbalancing Th-2 cytokines: IL-4, IL-5, IL-10, and IL-13; and the Th-17 cytokine IL-17A, which is actively involved in several autoimmune diseases including MS." (PMID 38932415, 2024). "While IL-17 is a strong proinflammatory cytokine associated with host defense against bacterial and fungal infections and is also elevated in several autoimmune diseases, IL-5/IL-13 and Arg1-positive M2 macrophages are part of the anti-inflammatory type 2 (Th2) immunity." (PMID 28680858, 2017). "Understanding the specifics of this IL-4/IL-5 axis in regards to B cell function could provide new targets for the design of therapeutic strategies for patients with autoimmune disorders or other inflammatory conditions." (PMID 23940537, 2013). "Firstly, we detected IL-2, IL-4, IL-5, IL-13, IL-17A, IL-17F, IL-22, IFN-γ, and TNF-α in the plasma to exclude the influence of infection or autoimmune disorders, and the standard curves were verified." (PMID 38343544, 2024). "Therefore, in assessing patients with autoimmune disorders, the measurement of Th1 (IFN-γ), Th2 (IL-4, IL-5, IL-13) and Th17 (IL-17) cytokine production by cultured lymphocytes will guide CAM practitioners in tailoring proper treatments for Th1- and Th17-mediated autoimmune diseases." (PMID 19622600, 2011).
Arthritis (22 papers, 2005 to 2025). Inflammation of a joint. "IL-5 transgenic (IL-5tg) mice, with remarkable hypereosinophilia, demonstrated a substantial decrease in arthritis scores in a serum-induced arthritis model of K/BxN, while eosinophil-deficient animals had increased disease activity." (PMID 40786589, 2025). "Resolution of arthritis was associated with the emergence of a regulatory eosinophil subset expanding in response to IL-5 derived from lung ILC2 and was further present in the synovium of rheumatoid arthritis patients in remission, but not in active stage." (PMID 37326974, 2023). "In the K/BxN serum-induced arthritis model, IL-5 transgenic (IL-5tg) mice that have extraordinary hypereosinophilia showed a significant reduction of arthritis score, whereas eosinophil-deficient ΔdblGATA mice presented with higher disease activity." (PMID 34733292, 2021). "Additional experiments using IL-5 triggered eosinophil differentiation or using eosinophil deficient mice provided clear evidence that eosinophils beneficially influence the course of arthritis." (PMID 27273006, 2016). "Interestingly, in an adjuvant-free arthritis model an increased IL-4 and IL-5 production was associated with eosinophil infiltration in ROS deficient mice." (PMID 24358335, 2013). "The development of arthritis was accelerated and characterized by increased circulating levels of IL-1β and reduced IL-5." (PMID 40370470, 2025). "An increase in IL-5 in JIA patients can serve as a marker indicating the autoimmune nature of inflammatory bone damage in the case of arthritis of an unspecified nature." (PMID 38255240, 2024). "Regarding the effect of ILC2s on the initiation phase of arthritis, IL-4(+)/IL-5(+)/IL-13(+) ILC2 numbers are increased from the beginning of arthritis in mice." (PMID 35163028, 2022). "The induction of IL-4/IL-5/IL-13(+) ILC2s mitigated arthritis, suggesting the inflammation is regulated by ILC2s." (PMID 35163028, 2022). "Key type 2 cytokines, like interleukin (IL)-4 and IL-13, but also others such as IL-5, IL-9, IL-25, and IL-33, exert regulatory properties on arthritis, dampening inflammation and inducing resolution of joint swelling." (PMID 35163028, 2022). "This synovial rEOS expanded on systemic up-regulation of IL-5 released by lung ILC2s in patients with RA remission, and anti-IL-5 antibody therapy induced the relapse of arthritis." (PMID 36181091, 2022). "In arthritis models, IL-5 is expressed in the arthritic joint synovium, and eosinophilic infiltration at the local joint modulated the resolution of arthritis by IL-5." (PMID 35163028, 2022). "In contrast, Il5tg mice and, to a lesser extent, also IL-5 treatment of WT mice led to significant reduction of arthritis scores." (PMID 27273006, 2016). "The affected 5q LOH interval harbors several cytokine genes (including IL-3, IL-4, IL-5, IL-13, and CSF2), a gene associated with arthritis susceptibility (SLC22A4), a DNA repair gene (RAD50), and a gene that promotes Type 1 interferon responses (IRF1)." (PMID 25107306, 2014). "IL-5 and IL-13 are cytokines related to arthritis suppression, while tissue-destructive cytokines IL-1β and IL-6 induce Th17 cells and promote osteoclastogenesis." (PMID 24456966, 2013). "Interestingly, RA patients with concomitant asthma who were in remission for arthritis experienced a relapse of arthritis after treatment with mepolizumab, an IL-5-neutralizing monoclonal antibody that depletes eosinophils." (PMID 40183859, 2025). "Notably, in patients with rheumatoid arthritis and concomitant asthma, the depletion of eosinophil with an anti–IL-5 antibody (mepolizumab) induced relapse of arthritis in a majority of cases." (PMID 37326974, 2023). "Furthermore, IL-5-producing cells were increased already early and returned to baseline level 6 days after induction of arthritis." (PMID 27273006, 2016). "In addition, recombinant IL-5, known to induce eosinophils, was injected into WT mice before and during induction of arthritis." (PMID 27273006, 2016).
Arthritis (continued). "The mice were injected with anti-IL-4, IL-5 or IL-13 blocking monoclonal antibody (mAb) on day 3 before (−3d) and day 3 after (+3d) the second immunization with CII, and the incidence of arthritis was monitored." (PMID 27812008, 2016). "Significant concentration differences in IL-5 in synovial fluid were noted between subjects with little or no arthritis compared to those with advanced arthritis based on the ICRS scale." (PMID 33996964, 2021). "Since B cells stimulated with IL-5 and CD40L secrete IL-10 and are potent inducers of apoptosis in activated T cells, we have made several attempts to assess their immunosuppressive function in vivo by adoptive transfer in a collagen-induced arthritis model." (PMID 23940537, 2013). "IL-5 mRNA underwent a gradual, moderate rise until day 3; for this cytokine, a negative correlation with the severity of arthritis was observed on day 6 (P < 0.001), although the group as such showed no significant IL-5 elevation on this date." (PMID 15899031, 2005). "The levels of IL-3, IL-5, IL-9, and LIF, as well as those of GM-CSF and VEGF, did not increase in the setting of CFA-induced arthritis." (PMID 36293292, 2022).
Autoimmunity (22 papers, 2012 to 2024). The occurrence of an immune reaction against the organism's own cells or tissues. "Further work is needed in examining the role of IL-5 in autoimmunity, however, as mice deficient in IL-5 appeared to have a similar clinical course of EAE." (PMID 23940537, 2013). "However, Th2-type cytokines (such as IL-4, IL-5, IL-10, etc.)can lead to less autoimmunity, susceptible to infections, and also may induce pregnancy-tolerance to fetus, providing protection to pregnancy." (PMID 25563385, 2015). "Alternatively, IL-5 is previously shown to promote induction of CD4+CD25+ T-regulatory cells that are involved in the suppression of autoimmunity." (PMID 34067512, 2021). "Another study reported that the addition of Gal-3BP induced suppression of IL-4, IL-5, and IL-13, Th2-type cytokines related to autoimmunity." (PMID 31402917, 2019). "IL-5 promotes the expansion and survival of antigen specific T regulatory cells (Treg), and treatment with recombinant IL-5 leads to an expansion of Treg and reduces pathology in experimental autoimmunity." (PMID 31333650, 2019). "Increased production of IL-2 promotes immunological tolerance and ameliorates autoimmunity by stimulating T regs growth and survival, while more IL-4 and IL-5 indicates a shift towards a Th2 phenotype, which is immunosuppressive in MS and EAE." (PMID 26140285, 2015). "Perhaps, local IL-5 levels combined with antigen unmasking drive autoimmunity to EBA and BP." (PMID 34067512, 2021). "IL-5 promoted induction of antigen-specific CD4+CD25+ TReg cells that suppress autoimmunity." (PMID 27095999, 2015). "We propose that one of the beneficial effects of parasites may be the high IL-5 level produced by a chronic Th2 response, promotes IL-5Rα expressing antigen specific Ts2 cells to control autoimmunity and allograft rejection." (PMID 23935597, 2013). "Parasites induction of immune responses that promote Treg, possibly by production of IL-5, may also explain the reduced incidence of autoimmunity in populations that live closer to the equator and have poorer hygiene." (PMID 23935597, 2013). "IL-5, IL-6, IL-13, IL-17, IL-23, and TNF-α are targetable with biologics developed for spontaneous autoimmunity, and our data broadly support the prospective investigation of these inhibitors for patients with irAEs." (PMID 39403935, 2024). "Additionally, IL-5 has been shown to induce the formation of antigen-specific T-REG cells and prevent autoimmunity." (PMID 38946402, 2024). "In the presence of CIndU, atopy and autoimmunity, there is no decrease in IL5-6th month compared to IL5-3rd month and baseline." (PMID 38795119, 2024).
lung carcinoma (21 papers, 1998 to 2025). "Ten blood cytokine levels, including; granulocyte-macrophage colony-stimulating factor, TNF (alpha), and IFN (gamma), IL1, IL6, IL12, IL4, IL8, IL10, IL5, were compared between 296 European-Americans and 170 African-Americans to determine their associations with lung cancer." (PMID 36874133, 2023). "The cytokines produced by “Type 2” immune cells (including ILC2s), IL-5, IL-13 and IL-4, were increased in both PLs and mPEs from lung cancer patients as compared to HD PLs." (PMID 40993215, 2025). "For example, T-cell lymphoma, classic Hodgkin lymphoma, SM, AML, MPN, and certain solid tumors (e.g., lung cancer, renal cell carcinoma, etc.)can abnormally release IL-2, IL-3, IL-5 or GM-CSF." (PMID 38611061, 2024). "The IL-5 levels provided the following outcome for lung cancer (p = 2.49E-02; OR 95% CI = 1.46 (1.05, 2.03))." (PMID 39267832, 2024). "reports that IL-33 treatment enhances ILC2 IL-5 immune response in the lung, thus activating eosinophils that subsequently suppress vital, anti-tumor Th-1 immunity, and lending to increased lung cancer metastasis and mortality." (PMID 34531874, 2021). "In lung cancer for instance, certain cytokines (IL-4, IL-5, IL-8, IL-10, IFN-γ, and TNF-α) were significantly elevated among EA compared to AA patients, whereas elevated IL-1β, IL-10, and TNF-α levels were associated with lung cancer only among AA patients." (PMID 32714862, 2020). "ILC2s can also produce IL-5, leading to eosinophil activation and an increased anti-tumor immune response in lung cancer." (PMID 31024531, 2019). "We next examined IL-4, IL-5, IL-6, and IL-13 levels in BAL, since IL-4, IL-5, and IL-13 are major mediators of allergic inflammation and IL-6 gene polymorphisms have been associated with increased lung cancer risk in asthmatics." (PMID 20796309, 2010). "Similarly, the role of IL-5 in MI and lung cancer has been established." (PMID 40270498, 2025). "For lung cancer, high intra-tumoral concentrations of CXCR2 ligands (CXCL1, CXCL5, and CXCL8) and type 2 cytokines IL-4, IL-5, IL-10, and IL-13 have been reported for non-small cell lung cancer." (PMID 26231039, 2015). "MR-PRESSO outlier testing validated the significant MR findings, except for monocyte chemoattractant protein-3 (MCP-3) in lung cancer (including different pathologic types), and macrophage migration inhibitory factor (MIF) and IL-5 in small-cell lung carcinoma, where limited SNPs were available." (PMID 38957317, 2024). "IL-5 production was observed in MNCs from lung cancer patients stimulated with IL-2, but not with IL-15." (PMID 9744501, 1998).